CITED2 (Cbp/p300 interacting transactivator with ED-rich tail 2)
Diseases named in the same sentence as CITED2 in open-access papers (continued):
Sharing a sentence is not in itself a finding about the gene and the disease.
bone marrow failure (1 paper, 2025).
chronic myeloid leukemia (1 paper, 2023). "In addition, pioglitazone depletes stem cells via decreased STAT5, HIF2α, and carboxy-terminal domain 2 (CITED2) expression in chronic myeloid leukemia (CML) and potentiates the effect of imatinib." (PMID 37370809, 2023).
coloboma (1 paper, 2007). An abnormality in which a part of a structure in one or both eyes is missing.
coronary heart disease (1 paper, 2025). "After testing the blood samples of children with coronary heart disease, it was found that there were four different types of mutations in the coding region of CITED2, all of which were located in the SGJ region at its carboxyl‐terminal." (PMID 39907030, 2025).
E. coli infection (1 paper, 2020). "Methylation and expression level validation experiments demonstrated that the CITED2 and SLC40A1 expression levels increased, and methylation levels decreased after E. coli infection." (PMID 32000686, 2020).
Ewing sarcoma (1 paper, 2019). A small round cell tumor that lacks morphologic, immunohistochemical, and electron microscopic evidence of neuroectodermal differentiation. "Notably, on this list, we observed both well-established and candidate oncogenes in Ewing sarcoma, with many of which displayed striking Ewing sarcoma-specific expression profiles (e.g. LINGO1, HOOK1, CITED2 and IGF2BP1)." (PMID 30496486, 2019).
gastroparesis (1 paper, 2023). Paralysis of the muscles of the stomach wall resulting in delayed emptying of the gastric contents into the small intestine. "Interestingly, MYH2 and CITED2 are known to be dysregulated in T2D, indicating that, unless the patients suffer from gastroparesis, the underlying diabetic condition does not show differences in gene expression patterns in gastric body biopsies." (PMID 37218990, 2023).
hyperprolactinemia (1 paper, 2023). Abnormally high level of prolactin in the blood. "This increase may be explained by the observed hyperprolactinemia since prolactin and STAT5 are known transcriptional activators of CITED2, HSPA5 and PIM1." (PMID 36694114, 2023).
idiopathic pulmonary arterial hypertension (1 paper, 2025). A sporadic form of pulmonary arterial hypertension (PAH) characterized by elevated pulmonary arterial resistance leading to right heart failure. "In addition, the expression of CITED2 and FOXJ3 also decreased in both the patients with idiopathic pulmonary arterial hypertension (iPAH) and the human PASMCs exposed to hypoxia." (PMID 39907030, 2025).
ischemic cardiomyopathy (1 paper, 2025). Ischemic cardiomyopathy is a cardiomyopathy in which a weakness in the muscle of the heart due to inadequate oxygen delivery to the myocardium with coronary artery disease being the most common cause. "Interestingly, the decrease in CITED2 expression has been associated with impaired cardiac function in human ischemic cardiomyopathy, emphasizing its potential importance in disease mechanisms and as a possible therapeutic target." (PMID 41295244, 2025). "However, patients with ischemic cardiomyopathy or a cardiomyopathy caused by infection with the protozoan Trypanosoma cruzi (Chagas disease) exhibit lower CITED2 transcript levels compared to control individuals." (PMID 41295244, 2025). "Together, these observations argue that CITED2 expression preserves the function of adult hearts during adverse ischemic cardiomyopathy." (PMID 41295244, 2025).
malignant glioma (1 paper, 2021). A grade III or grade IV glioma arising from the central nervous system. "Previous research has shown that childhood malignant gliomas involve abnormal methylation and silencing of LHX9,108 and the relationship between ISG20, CITED2, and LHX9 with OV and its molecular mechanism must be examined in depth in future studies." (PMID 34609082, 2021).
mastitis (1 paper, 2020). Inflammation of breast tissue during lactation or postpartum due to an obstructed duct or infection. "The expression levels of the CITED2 and SLC40A1 genes in mastitis cows were significantly higher in healthy cows (P < 0.05)." (PMID 32000686, 2020). "The relative expressions of CITED2 and SLC40A1 in healthy and mastitis cow blood neutrophils were detected using real-time PCR." (PMID 32000686, 2020).
metastatic colorectal cancer (1 paper, 2021). "However, the CITED2 and DKC1 genes were not reported in the metastatic colorectal cancer samples (MSKCC, Cancer Cell 2018, 1134 samples)." (PMID 34830168, 2021).
metastatic tumors (1 paper, 2018). "However, considering that a kind of cytokine storm occurs in tumor microenvironment, CITED2 could be differentially expressed in primary and metastatic tumors because they grow with distinct stromal cells." (PMID 30291252, 2018).
mood disorder (1 paper, 2022). A cognitive disorder a disturbance in which the person's mood is hypothesized to be the main underlying feature. "We found a significant overlap for 6 hub genes (ADM, CITED2, IER5, NFKBIZ, SERTAD1, TNF) with similar co-expression and dysregulation patterns associated with mood disorder." (PMID 35386281, 2022).
pericardial effusion (1 paper, 2019). Fluid collection within the pericardial sac, usually due to inflammation. "Decrease of heart rate is a sign of cardiac dysfunction which was further confirmed by the presence of pericardial effusion and cardiac anomalies such as linear heart tube, enlarged heart chambers or the presence of a virtually unique chamber in Cited2-morphants." (PMID 31378782, 2019).
premature ovarian failure (1 paper, 2022). "Human variants in CITED2, such as in NR5A1, are associated with premature ovarian failure (POF)." (PMID 36013096, 2022).
prostate tumor (1 paper, 2018). "The results showed that prostate tumor growth was delayed by CITED2 or NCL knockdown." (PMID 30291252, 2018).
pulmonary hypertension (1 paper, 2025). Increased pressure within the pulmonary circulation due to lung or heart disorder. "Lentiviral overexpression of CITED2 also reversed hypoxia‐induced pulmonary hypertension mice model." (PMID 39907030, 2025).
reovirus infection (1 paper, 2018). "Transcripts that were up-regulated and stabilized following reovirus infection included SMAD 1, 2, 6 &7, Tgif, c-Myc, CITED2 and KLF5, which encode components of the SSN that control transcription of genes that regulate apoptosis and cell growth." (PMID 30261045, 2018).
sarcoma (1 paper, 2023). A usually aggressive malignant neoplasm of the soft tissue or bone. "PRDM10 gene fusions with either MED12 or CITED2 have been reported in a small proportion of undifferentiated pleomorphic sarcomas." (PMID 36440963, 2023).
Sepsis (1 paper, 2023). Sepsis is defined as life-threatening organ dysfunction caused by a dysregulated host response to infection. "Myeloid-CITED2-deficient mice are highly prone to endotoxin-induced sepsis symptomology, HFD-induced atherosclerotic plaque development, and zymosan-induced lung inflammation in vivo." (PMID 37681868, 2023).
serous ovarian tumors (1 paper, 2021). "Upregulation of CITED2 is related to shorter recurrence times in serous ovarian tumors." (PMID 34950205, 2021).
spina bifida (1 paper, 2010). A congenital neural tube defect in which vertebrae are not fully formed. "Three single nucleotide polymorphisms (SNP) in the un-translated region of CITED2 gene were studied in a group of patients with spina bifida and controls, modest associations were observed but results were imprecise owing to small sample size." (PMID 20932315, 2010). "The purpose of this study is to evaluate the potential association between variations among human CITED2, CREBBP, EP300, TFAP2A, CARM1 and ALX1 genes and the risk for spina bifida." (PMID 20932315, 2010). "We have observed modest associations with risk of spina bifida in CITED2, EP300, CREBBP, TFAP2A and CARM1 genes but not ALX1 gene." (PMID 20932315, 2010).
spinal cord injury (1 paper, 2026). Penetrating and non-penetrating injuries to the spinal cord resulting from traumatic external forces (e.g., WOUNDS, GUNSHOT; WHIPLASH INJURIES; etc.). "We identify the transcriptional co-regulator CITED2 as a key epigenetic switch, active in immature and regenerating DRG neurons but silent after non-regenerative spinal cord injury (SCI)." (PMID 41731079, 2026).
ulcerative colitis (1 paper, 2016). An inflammatory bowel disease involving the mucosal surface of the large intestine and rectum. "Currently, no clinical studies of CITED2 in CRC are available, although CITED2 protein expression is increased in ulcerative colitis, a condition often associated with CRC." (PMID 26243458, 2016).
undifferentiated sarcoma (1 paper, 2022). "Additional undescribed fusions included EPC2-AFF3 and MAN1A2-ACBD6 identified in two patients with undifferentiated sarcoma, and a CITED2-MGA fusion in a round-cell sarcoma not otherwise specified." (PMID 35585047, 2022).
tumor (27 papers, 2009 to 2026). "CITED2 has been identified as a co-transcription factor implicated in stem and tumor cell proliferation and apoptosis." (PMID 40313859, 2025). "The transcription factor Cbp/p300-interacting transactivator with Glu/Asp-rich carboxy-terminal domain 2 (Cited2) has been implicated in the control of tumor cells and mesenchymal stem cell (MSC) and cardiomyocyte growth or migration." (PMID 38419888, 2024). "It is also reported that CITED2 knockdown caused tumour shrinkage and increased overall host mouse survival rates." (PMID 28330331, 2016). "CITED2 mainly acts as a promoter in many tumour cells, and many experiments have shown that CITED2 plays an inhibitory role in the process of cell proliferation." (PMID 39907030, 2025). "In clinical samples analysed by TCGA, the expression of 5 genes, CCL20, IL1B, IL24, PLAU and SEMA7A, was significantly higher in the primary tumour than in solid normal tissue, whereas that of CITED2 was lower." (PMID 38363001, 2024). "For example, the complete ARBS landscape of CITED2 (PCa tumor-driving gene) has a high degree of ARBS heterogeneity including many PS- and UN-ARBS scattered between individual tumors on Chr6." (PMID 36450752, 2022). "Here, we show that CITED2 silencing significantly attenuated MDA-MB-231 primary tumor growth concordant with reduced tumor vascularization, while MDA-MB-468 primary tumor growth and tumor vascularization remained unaffected." (PMID 28008154, 2017). "The inability of CITED2 silencing to impact MDA-MB-231 cell proliferation in vitro suggested that the reduced tumor growth displayed by shCITED2-expressing MDA-MB-231 tumors was due to an indirect effect." (PMID 28008154, 2017). "Both NCOR2 and CITED2 mRNA levels were associated with MFS, that is, tumour aggressiveness, independently of traditional prognostic factors." (PMID 19904269, 2009). "Given the impact of the viral integrations within NCOR2 and CITED2 on the overall mRNA expression in our cell model, we established their relationships with clinical parameters reflecting tamoxifen resistance and tumour aggressiveness." (PMID 19904269, 2009). "High expression of CITED2 promotes tumor growth and correlates with poor prognosis." (PMID 40313859, 2025). "Firstly, the underlying mechanism of the 6 identified PGRs, especially CITED2, EXOC6B, MIA2, and TRPV4, in OV progression and tumor immune microenvironment remained largely unknown, which needs stepwise investigation." (PMID 37730669, 2023). "However, only a few investigations have been conducted on the role of CITED2 in tumor development during the last decade." (PMID 30291252, 2018). "Thus, it will be important to identify CITED2 binding partners and consider their expression alongside that of CITED2 in order to gauge its potential impact in a given tumor." (PMID 28008154, 2017). "Thus, FAM46C-meditated RNA stability and CITED2 hypoxic response may play a role in the FAM46C-meditated tumor heterogeneity." (PMID 37155154, 2023). "Immunohistochemistry (IHC) staining and western blotting of tumor xenografts 5 days post treatment confirmed significant downregulation of p300/CBP, AR, PSA, MYC, Ki67, CCND1, NKX3-1, CITED2, H3K27ac and H2BK20ac." (PMID 41044247, 2025). "Consistent with our in vitro findings, immunohistochemistry (IHC) staining and western blotting of tumor xenografts five days post treatment confirmed significant downregulation of p300/CBP, AR, PSA, MYC, Ki67, CCND1, NKX3–1, CITED2, H3K27ac, and H2BK20ac." (PMID 38586029, 2024). "CITED2, widely expressed, binds competitively to the CH1 domain of CBP/p300, a transcriptional co-activator, counteracting HIF-1, which is essential for tumor cell adaptation to hypoxic environments." (PMID 39388011, 2024). "In tumor tissue homogenates obtained from mouse xenograft, protein expressions of CITED2 and NCL were measured to verify the overexpression or knockdown of CITED2 and NCL." (PMID 30291252, 2018).
tumor (continued). "CITED2, on the other hand, interacts with Smad2 and Smad3 to induce expression of the matrix metalloproteinase 9 gene in TGF-β-mediated tumor cell invasion." (PMID 19883516, 2009). "Taken together, these data demonstrate that CITED2 silencing selectively alters MDA-MB-231 but not MDA-MB-468 tumor vessel formation." (PMID 28008154, 2017). "Since CITED2 silencing did not affect MDA-MB-468 tumor growth or vessel formation, we also examined VEGFA expression in scramble and shCITED2-expressing MDA-MD-468 tumors." (PMID 28008154, 2017). "Although CITED2 silencing did not affect the total number of blood vessels observed between the two tumor groups, vessels in the shCITED2-expressing tumors appeared shorter." (PMID 28008154, 2017). "Our results showed that in LNN patients with ERα-positive primary tumours who had not received systemic adjuvant treatment, high mRNA levels of NCOR2 and CITED2 were associated with a longer MFS independently of the traditional prognostic factors." (PMID 19904269, 2009). "Two candidate target genes, CITED2 and NCOR2, yielding distinct gene expression profiles when compared with other cell lines, were analysed for their clinical relevance in terms of tamoxifen resistance and tumour aggressiveness." (PMID 19904269, 2009). "Therefore, we cannot rule out the possibility that CITED2 is overexpressed in metastatic tumor milieu." (PMID 30291252, 2018). "CITED2 expression in other types of cancers was not significantly increased with tumor stage." (PMID 30291252, 2018). "Further, CITED2 silencing in these cells did not affect tumor cell proliferation in vitro." (PMID 28008154, 2017).
cancer (24 papers, 2010 to 2025). A tumor composed of atypical neoplastic, often pleomorphic cells that invade other tissues. "Generally, a reduction in CITED2 is linked to enhanced migration or proliferation of cancer cells." (PMID 41345200, 2025). "Epigenetic modifications, including DNA methylation and histone modifications, can also regulate CITED2 expression in cancer." (PMID 39907030, 2025). "Current studies have proven the functions of Cited2 in the apoptosis and proliferation of endothelial cells, cardiomyocytes, cancer cells, neuronal cells, and hematopoietic stem cells." (PMID 38419888, 2024). "Numerous studies have shown that CITED2 can promote cancer metastasis, cell proliferation, and apoptosis and participate in the regulation of various transcriptional responses." (PMID 31885738, 2019). "We next compared CITED2 levels between normal and cancer tissues using the Genomic Spatial Event (GSE) database." (PMID 30291252, 2018). "So, researchers found that Cited2 may play important roles in cancers, cardiovascular disease, and other metabolic diseases." (PMID 38419888, 2024). "Moreover, five genes, including CITED2, C8orf44‐SGK3, FUZ, P2RY1, and SIX2, were associated with carcinoma migration." (PMID 38363001, 2024). "Combination therapies targeting cancer cells and macrophages might have mutually synergistic effects.CITED2 alone had prognostic value in predicting overall GC survival by representing macrophage M2 properties." (PMID 35785171, 2022). "FOXO3 could respond to hypoxic stress and block HIF1-mediated apoptosis by regulating CITED2 in cancer cells, and HIF-1 related hypoxia pathways were acknowledged as working in RCC." (PMID 34461918, 2021). "Based on these results, the CITED2–NCL axis may activate signaling pathway(s) that strongly induce cancer metastasis." (PMID 30291252, 2018). "Previous studies have reported that CITED2 increases cancer progression." (PMID 30291252, 2018). "However, little is known about the role of CITED2 in cancer metastasis." (PMID 30291252, 2018). "CITED2 is a crucial mediator of the HIF1A hypoxic response, which, in cancer, is indicated to serve as a co-activator of SMAD2/3 affecting TGF-β signaling." (PMID 38339304, 2024). "The CITED2 stimulation of AKT translation strengthens AKT signaling to promote EMT and eventually cancer metastasis." (PMID 30291252, 2018).
heart disease (4 papers, 2016 to 2025). "CITED2 has also been linked with some heart diseases, which may be of note since birds and small bats possess larger hearts relative to vertebrates of similar size." (PMID 27193938, 2016). "This complexity also emphasizes the importance of considering specific cell types when evaluating CITED2 as a potential therapeutic target in heart disease." (PMID 41295244, 2025). "Future research should focus on elucidating the precise molecular mechanisms by which CITED2 and CITED4 regulate cardiomyocyte function, and on exploring their potential as therapeutic targets to enhance cardiac repair and regeneration in heart disease." (PMID 41295244, 2025).
infection (3 papers, 2010 to 2024). The state of being infected such as from the introduction of a foreign agent such as serum, vaccine, antigenic substance or organism. "Upon infection, a distinct phenotype (subcluster 7.1) emerged among infected cells that shared markers with the highly infected cluster 4, including CITED2, FOS, TXNIP, and CCNG2 genes." (PMID 38896609, 2024).
neurodevelopmental disorder (1 paper, 2022). A behavioral and cognitive disorder with onset during the developmental period that involves impaired or aberrant development of intellectual, motor, or social functions. "Further, forebrain-specific Cited2 conditional knockout (cKO) leads to behavioral deficits associated with human neurodevelopmental disorders, highlighting the importance of CITED2 in cognitive function." (PMID 36248641, 2022).